HGFAC (HGF activator)
Description:
Serine protease that hydrolyzes the inactive zymogen hepatocyte growth factor (HGFsc) to an activated disulfide-linked heterodimer, then initiating hepatocyte growth factor receptor signaling pathway.
Synonyms: HGFA; HGFAP
Tractability: Small molecule: a high-quality ligand is known; it belongs to a druggable protein family. Antibody: UniProt places it where antibodies can reach, with high confidence; its Gene Ontology location is reachable by antibodies, with high confidence; UniProt predicts a signal peptide or a membrane-spanning region. PROTAC: a small molecule that binds it is known.
Target class: Serine protease; Enzyme; Serine protease PA clan; Serine protease S1A subfamily; Protease
Gene: Protein-coding gene on chromosome 4 (3,441,924 to 3,449,493, forward strand). Ensembl gene ENSG00000109758.
Subcellular location: Secreted
Pathways (Reactome):
Signal Transduction: MET Receptor Activation
Gene Ontology:
Molecular function: protein binding; serine-type endopeptidase activity; serine-type peptidase activity
Biological process: blood coagulation; proteolysis; zymogen activation
Cellular component: extracellular region; cytosol; rough endoplasmic reticulum; cytoplasm
Genetic constraint (gnomAD): Loss-of-function variants: 76 observed, 56.08 expected, observed/expected ratio (o/e) 1.36, 90% interval 1.12 to 1.64. The synonymous counts are far from expectation, so gnomAD's model fits this gene poorly and the ratio says little. Missense variants: 1,039 observed, 840.57 expected, observed/expected ratio (o/e) 1.24, 90% interval 1.17 to 1.3. Synonymous variants: 462 observed, 359.97 expected, observed/expected ratio (o/e) 1.28, 90% interval 1.19 to 1.39.
Homologues: Orthologues: chimpanzee HGFAC (99% identical), macaque HGFAC (95% identical), dog HGFAC (84% identical), mouse Hgfac (81% identical), rat Hgfac (80% identical), pig HGFAC (79% identical), guinea pig HGFAC (73% identical), tropical clawed frog hgfac (47% identical). Paralogues in human: F12 (36% identical), KLKB1 (21% identical), F11 (20% identical), C1R (19% identical), C1S (19% identical), F7 (18% identical), F9 (18% identical), F10 (17% identical), CFI (16% identical), C1RL (14% identical), PRSS55 (14% identical), CFD (12% identical), and 4 more.
Diseases named in the same sentence as HGFAC in open-access papers:
HGFAC is named in the same sentence as 73 diseases in open-access papers, as found by Europe PMC text mining. Sharing a sentence is not in itself a finding about the gene and the disease. The quoted sentences say what the papers report.
breast carcinoma (3 papers, 2015 to 2021). "Production of large amounts of the HGF activator (HGFA), stimulating expression of HGF in stromal cells, has been previously demonstrated in highly invasive breast cancer cells such as MDA-MB-231 that also overexpress the HGF receptor c-met." (PMID 25880005, 2015). "Furthermore, HGF activator (HGFA), a soluble protease, has been reported to be expressed in multiple breast cancer cell lines and in human breast tumors." (PMID 27528224, 2016).
COVID-19 (3 papers, 2020 to 2024). A disease caused by infection with severe acute respiratory syndrome coronavirus 2. "The alpha-2-HS-glycoprotein (AHSG) and the hepatocyte growth factor activator (HGFAC) were the only two proteins downregulated by COVID-19 across all severity groups; the rest of the proteins were differentially expressed in a severity-dependent manner." (PMID 38791465, 2024). "According to these criteria, we found four procoagulants (ADAMTS13, F11, HGFAC, KLKB1) and two anticoagulants (C1QTNF1, SERPINA5), whose expression may predispose males and older individuals to COVID-19-related coagulopathy and severe COVID-19 disease." (PMID 32751741, 2020).
colorectal cancer (2 papers, 2008 to 2017). A primary or metastatic malignant neoplasm that affects the colon or rectum. "Some of these variants occur within genes related to diseases that are known to be more commonly diagnosed in the AJP than in NJPs: colorectal cancer (APC gene) and pancreatic cancer (HGFAC gene)." (PMID 28502252, 2017).
Insulin resistance (2 papers, 2023). Increased resistance towards insulin, that is, diminished effectiveness of insulin in reducing blood glucose levels. "Furthermore, AFM, GSN, CFH, HGFAC, MMP2, and MMP9 have been previously associated with NAFLD or NAFLD-related factors such as liver damage, insulin resistance, metabolic syndromes, and extracellular homeostasis." (PMID 38034020, 2023). "Interestingly, Hgfac global knockout mice exhibit reduced hepatic and increased circulating triglyceride concentrations respectively, with a parallel glucose intolerance and insulin resistance, suggesting that HGFAC plays a key role in the regulation of lipid clearance and glucose homeostasis." (PMID 36923222, 2023).
liver cancer (2 papers, 2021 to 2025). An epithelial or non-epithelial malignant neoplasm that arises from the liver. "Furthermore, the reduction in HGFAC expression is significantly associated with a shortened survival period in liver cancer patients." (PMID 40932836, 2025).
Obesity (2 papers, 2022 to 2023). Accumulation of substantial excess body fat. "Additionally, hepatic HGFAC mRNA expression is upregulated in patients with obesity and uncontrolled diabetes, conditions that are associated with increased hepatic ChREBP activity." (PMID 36413406, 2023). "Collectively, these data support the hypothesis that hepatic HGFAC expression and circulating levels of HGFAC are regulated by ChREBP activity both in rodents and in humans, and hepatic HGFAC expression is increased in obesity and diabetes." (PMID 36413406, 2023).
adenomyosis (1 paper, 2025). The growth of endometrial tissue inside the muscular wall of the uterine corpus. "The termination variant detected in Hepatocyte Growth Factor Activator (HGFAC) highlights it as a plausible candidate gene for adenomyosis, given its role in activating HGF, which in turn promotes epithelial–mesenchymal transition (EMT) and drives glandular invagination into the myometrium." (PMID 41374450, 2025).
bladder cancer (1 paper, 2025). "In addition, no apparent statistical correlation was also observed between the expression of HGF, MET, ST14, HPN, and HGFAC and the prognosis of patients with bladder cancer by GEPIA." (PMID 40299447, 2025).
breast ductal carcinoma (1 paper, 2021). "HGFAC expression is directly correlated to survival in breast ductal carcinoma and ovarian carcinoma." (PMID 34090518, 2021).
colitis (1 paper, 2023). Inflammation of the colon. "Animal experiments showed that HGFAC knockout mice are more susceptible to dextran sulfate sodium-induced colitis compared to wild-type mice." (PMID 36857861, 2023).
hypogonadism (1 paper, 2025). A disorder characterized by decreased function of the gonads. "Protein-coding variants in several liver genes, such as PNPLA3, GCKR, SLCO1B1, SERPINA1, HGFAC, and UGT2B15, were significantly associated with total testosterone levels and hypogonadism risk." (PMID 40316537, 2025).
insulinomas (1 paper, 2015). "An interesting finding of the present study was the absence of RNA expression of HGFAC, considered the most powerful activator of pro-HGF in HGF, indicating that in insulinomas, matriptase (and maybe other proteins not evaluated in this study, such as hepsin) is responsible for pro-HGF proteolysis." (PMID 26435753, 2015).
lung carcinoma (1 paper, 2017). "Intrigued by these observations, we extended the analysis to HGFAC and SPINT1; note, these were up-regulated in murine lung cancer tissues and are potential c-Myc target genes." (PMID 29254206, 2017).
macular degeneration (1 paper, 2014). Loss of vision in the central portion of the retina (macula), secondary to retinal degeneration. "Four of 12 nsSNP-phenotype associations were successfully replicated in an independent data set: thrombosis (F5,rs6031), seizures/convulsions (GPR98,rs13157270), macular degeneration (CNGB3,rs3735972), and GI bleeding (HGFAC,rs16844401)." (PMID 24949630, 2014).
overnutrition (1 paper, 2023). An imbalanced nutritional status resulting from excessive intake of nutrients. "Together, our studies show that ChREBP mediated an adaptive response to overnutrition via activation of HGFAC in the liver to preserve glucose and lipid homeostasis." (PMID 36413406, 2023). "Therefore, elevated ChREBP/HGFAC/HGF may promote healthy expansion of adipose tissue for efficient storage of fuel during overnutrition." (PMID 36413406, 2023).
tobacco use disorder (1 paper, 2022). "Three novel genes—SLC39A8, GRK4 and HGFAC—within loci associated with altered alcoholic drinks per week (ADW) or cigarettes per day (CPD) were selected to further study their role in alcohol and tobacco use disorder." (PMID 35661789, 2022).
tumor (25 papers, 2008 to 2025). "To determine if miR-4270 mediates its tumor-suppressive role in HCC cells through HGFAC regulation, we conducted rescue experiments involving co-transfection with the miR-4270 inhibitor and pcDNA-HGFAC plasmid." (PMID 38077422, 2023). "HGFAC is a novel serine protease that activates the precursor of hepatocyte growth factor and promotes angiogenesis, tumorigenesis, and regeneration in the tumor microenvironment." (PMID 38077422, 2023). "Consistent with the in vitro findings, HGFAC protein levels increased significantly, and DNMT3A levels were decreased in tumor tissues from nude mice with increased miR-4270 expression." (PMID 38077422, 2023). "This is achieved by one of the trypsin-like serine proteases, matriptase, hepsin or HGF activator (HGFA), which are expressed by tumor cells." (PMID 28968967, 2017). "The trypsin-like serine proteases, matriptase, hepsin and HGF activator (HGFA), which are commonly over-expressed in tumor cells, are three principal proteases responsible for HGF activation." (PMID 28420162, 2017).
cancer (8 papers, 2007 to 2021). A tumor composed of atypical neoplastic, often pleomorphic cells that invade other tissues. "Hepatocyte growth factor activator (HGFAC), an activator of hepatocyte growth factor (HGF), has been previously reported to be involved in liver regeneration in response to injury and several types of cancers." (PMID 33879119, 2021).
metabolic disease (1 paper, 2023). A congenital disorder (due to inherited enzyme abnormality) or acquired (due to failure of a metabolically important organ) disorder resulting from an abnormal metabolic process. "The most significant novel shared SNP was rs59950280 (PCPASSOC = 1.33 × 10–10) located near HGFAC, encodes a member of the peptidase S1 protein family, an enzyme activating hepatocyte growth factor (HGF), which further influence metabolic diseases and CVD." (PMID 37705021, 2023).
HGFAC also shares sentences with these, for which no sentence is quoted: microcephaly (5 papers); brain tumor (4); Hydrocephalus (4); Ataxia (3); Crohn disease (3); glioma (3); medulloblastoma (3); myeloma (3); prostate carcinoma (3); astrocytoma (2); diffuse large B-cell lymphoma (2); gastric cancer (2); glioblastoma (2); infection (2); neuroendocrine tumors of the pancreas (2); pancreatic cancer (2); acute myeloid leukemia (1); Alexander disease (1); Anxiety (1); brain malformations (1); breast tumors (1); cerebellar tumors (1); cervical dystonia (1); CNS tumor (1); coagulopathy (1); colon cancer (1); convulsion (1); depression (1); diabetes (1); endometriosis (1).
A further 24 diseases each share a sentence with HGFAC in 1 paper.